PMS2 (PMS1 homolog 2, mismatch repair system component)
Diseases named in the same sentence as PMS2 in open-access papers (continued):
Sharing a sentence is not in itself a finding about the gene and the disease.
glioma (24 papers, 2013 to 2026). A benign or malignant brain and spinal cord tumor that arises from glial cells (astrocytes, oligodendrocytes, ependymal cells). "Because of a nuclear loss of PMS2 staining there was the suspicion of a diffuse paediatric-type high-grade glioma, H3-wildtype and IDH-wildtype." (PMID 37561227, 2023). "A high-grade glioma was diagnosed in seven patients, six of whom carried biallelic PMS2 mutations." (PMID 30013564, 2018). "The genes implicated in glioma risk play roles in DNA damage response, e.g., ATM, BRCA2, PMS2, POLE, or diverse other processes including metabolism, signal transduction, and cell cycle regulation." (PMID 41546701, 2026). "Haematological cancers were common among PMS2 or MSH6 mutation carriers, while gastrointestinal and CNS cancers were prevalent across all four MMR genes." (PMID 39247025, 2024). "A separate nonhypermutated glioma developed 2 yr later, and it was determined that the two tumors acquired distinct somatic second hits in the remaining PMS2 allele." (PMID 31604779, 2019). "To investigate whether age may influence abnormal DNA repair gene expression, and affect susceptibility to the development of gliomas, we assessed the association between APE1, NBN, PMS2, MGMT and PTEN mRNA expression and age." (PMID 25026297, 2014). "We speculate that PMS2 may have essential roles in adult glioma pathogenesis but detailed mechanistic studies are required to confirm this hypothesis." (PMID 25026297, 2014). "Chromosome 7, with frequent copy number gains in all four cancers, harbors several key oncogenes such as EGFR, CDK6, and MET in glioma; KMT2C and PMS2 in medulloblastoma; BRAF, RAC1, and TRRAP in melanoma." (PMID 41537310, 2026). "Amplification of the PMS2 gene is frequently found in glioblastoma multiforme (GBM, 454 [79.5%] of 571), lower grade glioma (LGG, 134 [22.4%] of 510), HNSC (205 [39.7%] of 517) and OV (132 [23.5%] of 562)." (PMID 32226530, 2020). "To evaluate the suitability of the antibody used here, we first investigated the protein expression of APE1, NBN, PMS2, and PTEN in LN229 and LN18 human glioma cell lines by Western blot analysis." (PMID 25026297, 2014). "Given the essential role of APE1, NBN, PTEN, PMS2 and MGMT in adult tumours we explored if these genes also influence outcomes in paediatric high grade gliomas/glioblastomas." (PMID 25026297, 2014). "Regarding the glioma report, the authors speculated that APE1 operates in conjunction with other DNA repair molecules, such as NBN, PMS2, MGMT and PTEN, to influence biological and clinical outcomes in glioma." (PMID 28938675, 2017). "To evaluate whether APE1, NBN, PMS2, MGMT and PTEN mRNA also have a role in paediatric high grade gliomas we proceeded to investigate mRNA expression in 53 paediatric high grade gliomas and 27 paediatric glioblastomas." (PMID 25026297, 2014).
glioma (continued). "Together the data implies that APE1, NBN, PMS2, MGMT and PTEN do not influence paediatric glioma pathogenesis." (PMID 25026297, 2014).
gastric cancer (22 papers, 2018 to 2025). A primary or metastatic malignant neoplasm involving the stomach. "While MLH1 is most commonly lost in MSI-related gastric cancers, one study saw loss of MLH1/PMS2 in only 88% of MSI-H cases, and thus a single marker is expected to miss at least 10% of the MMR-deficient cases." (PMID 31790410, 2019). "We might miss out MSI cases with the isolated loss of PMS2 or MSH6, although those may be exceptional, at the least, in gastric carcinomas." (PMID 32498695, 2020). "In gastric cancer, the MLH1-/PMS2- pattern was observed in 93.3% of cases, followed by PMS2- (3.3%), and MLH1-/MSH6-/PMS2- (3.3%)." (PMID 37953261, 2023). "Our study demonstrates that MLH1-/PMS2-/MSH6- digestive system cancer cases are a rare subgroup of dMMR cancers, that account for 1.4% of all cases in our cohort and do not only occur in CRCs but also in ampullary as well as gastric cancer." (PMID 36387226, 2022).
glioblastoma (21 papers, 2013 to 2026). The most malignant astrocytic tumor (WHO grade IV). "PMS2 mutations are associated with combined presence of multiple colorectal adenomas and glioblastomas (Turcot syndrome)." (PMID 28250766, 2017). "The data presented here, demonstrating that low PMS2 mRNA is associated with improved survival in adult glioblastoma patients, would concur with the improved survival seen in TS patients." (PMID 25026297, 2014). "In glioblastoma cells resistant to temozolomide treatment, a reduction in PMS2 protein was observed and knockdown of PMS2 in parental cells conferred this resistance." (PMID 26036629, 2015). "Importantly, for the remaining nine PGVs that were identified in genes with a strong association with familial glioblastoma or medulloblastoma (SUFU, MSH6 (2x), PMS2 (5x) and BRCA1), a second (somatic) event and/or a matching mutational signature was identified in the tumor." (PMID 41168197, 2025). "Although numbers remain small, a higher-than expected frequency of patients with glioblastoma carrying a PGV in MMR genes was seen, with the biggest difference for MSH6 and PMS2." (PMID 41168197, 2025). "In addition to known glioblastoma genes including ERBB2, PMS2, or CHI3L1, over 50 genes new genes were identified." (PMID 32025336, 2020).
pancreatic cancer (18 papers, 2016 to 2025). "Lastly, one patient with intestinal GC diagnosed at 51 years, with a family history of pancreatic cancer, harboured a pathogenic PMS2 variant (0.13%)." (PMID 40446793, 2025). "Biopsy confirmed the diagnosis of pancreatic cancer, and germline testing revealed the coexistence of BRCA2 and PMS2 mutations." (PMID 40880847, 2025). "Tier I or II mutations related to hereditary cancer syndrome in pancreatic cancer were identified in BRCA1 (n = 2, 2.3%), BRCA2 (n = 2, 2.3%), PRSS1 (n = 1, 1.1%), MSH6 (n = 2, 2.3%), PMS2 (n = 1, 1.1%), and APC (n = 1, 1.1%)." (PMID 36463295, 2022). "Another case was an Italian male diagnosed with pancreatic cancer at age 74 who harbored PSV in the BRCA2 and PMS2 genes." (PMID 39102164, 2024).
adenoma (16 papers, 2016 to 2025). A neoplasm arising from the epithelium. "This is consistent with a hybrid model: the initial mutation may cause an adenoma, and the second hit in the wild-type PMS2 allele may drive the adenoma towards become cancerous with MSI." (PMID 39849512, 2025). "In PMS2-deficient cancers and adenomas, it has been shown that the KRAS mutations take place earlier in the course of development than dMMR, which may indicate that MMR deficiency does not drive the carcinogenesis in PMS2-associated CRC42–44." (PMID 37165697, 2023). "Elevated adenoma burden has been shown in about 6% of LS patients, and multiple cumulative adenomas are particularly observed in carriers of pathogenic MSH6 and PMS2 gene variants as well as individuals with CMMRD." (PMID 38725616, 2024). "Information on dMMR crypts and dMMR adenomas incidences in path_MSH6 and path_PMS2 carriers is limited." (PMID 38741120, 2024). "Furthermore, PMS2 deficiency in adenomas is preceded by KRAS alterations, as is CRC in PMS2 variant carriers." (PMID 38473212, 2024). "Adenomas in patients with PMS2-associated CRCs do not exhibit CTNNB1 mutations; consequently, those carriers have a lower CRC risk." (PMID 36553592, 2022). "Moreover, it has been reported that MSH6 and PMS2 mutation carriers can benefit more from colonoscopy surveillance since MMR-DCF are both less common and less likely to progress along the adenoma–carcinoma sequence." (PMID 34201893, 2021). "In most LS patients CRC may arise from adenomas, although an alternative non-polypoid carcinogenesis pathway has been proposed for PMS2 carriers." (PMID 37168379, 2023).
hereditary cancer (16 papers, 2010 to 2025). Malignant neoplasms occurring in families at a rate greater than that expected by chance and caused by germline mutations in a specific gene. "The NGS analysis of 25 genes associated with hereditary cancer revealed a heterozygous germline missense variant in PMS2 (NM_000535.7: c.184G>A; p.Gly62Arg), which was confirmed by Sanger sequencing." (PMID 40723192, 2025). "Four variants classified as KP or EP in the BRCA2, PMS2, and SDHB genes have been recognized to cause different types of hereditary cancer." (PMID 30217213, 2018). "Other segdup regions, including NEB (exons 83–103), PMS2 (exons 12–15), PRSS1, and SDHA, accounted for 358 additional findings within the hereditary cancer, neurology, and pediatric indications." (PMID 34007000, 2021).
hereditary cancer syndrome (15 papers, 2016 to 2024). "The molecular diagnosis of PMS2 in hereditary cancer syndromes is challenging due to a family of pseudogenes highly homologous to PMS2." (PMID 37628631, 2023).